SLC25A15 (solute carrier family 25 member 15)
Description:
Mitochondrial ornithine-citrulline antiporter (Probable). Catalyzes the exchange between cytosolic ornithine and mitochondrial citrulline plus an H(+), the proton compensates the positive charge of ornithine thus leading to an electroneutral transport. Plays a crucial role in the urea cycle, by connecting the cytosolic and the intramitochondrial reactions of the urea cycle (Probable). Lysine and arginine are also transported by the antiport mechanism (Probable). In addition, catalyzes an electroneutral exchange of ornithine or lysine for H(+), a reaction driven by the pH gradient across the inner membrane (By similarity).
Synonyms: ORC1; ORNT1; lnc-HC; D13S327; HHH
Tractability: Antibody: UniProt predicts a signal peptide or a membrane-spanning region. PROTAC: ubiquitination databases record sites on it; its protein half-life has been measured.
Gene: Protein-coding gene on chromosome 13 (40,789,412 to 40,812,460, forward strand). Ensembl gene ENSG00000102743.
Subcellular location: Mitochondrion inner membrane; Mitochondrion membrane
Pathways (Reactome):
Disease: SLC25A15 variants cause hyperornithinemia-hyperammonemia-homocitrullinemia syndrome
Metabolism: Urea cycle
Gene Ontology:
Molecular function: antiporter activity; arginine:ornithine antiporter activity; L-arginine transmembrane transporter activity; L-lysine transmembrane transporter activity; L-ornithine transmembrane transporter activity
Biological process: L-arginine transmembrane transport; L-lysine transmembrane transport; mitochondrial L-ornithine transmembrane transport; urea cycle
Cellular component: mitochondrial membrane; mitochondrion; membrane; mitochondrial inner membrane
Genetic constraint (gnomAD): Loss-of-function variants: 24 observed, 32.89 expected, observed/expected ratio (o/e) 0.73, 90% interval 0.53 to 1.03. The upper end of that interval is the gene's LOEUF score, 1.03, which puts it in group 4 of 6, group 1 being the genes least tolerant of losing a copy. Missense variants: 317 observed, 388.76 expected, observed/expected ratio (o/e) 0.82, 90% interval 0.74 to 0.89. Synonymous variants: 132 observed, 148.89 expected, observed/expected ratio (o/e) 0.89, 90% interval 0.77 to 1.02.
Gene-disease validity (ClinGen):
ClinGen rates the evidence that SLC25A15 causes each of these diseases.
ornithine translocase deficiency (autosomal recessive): Definitive.
Homologues: Orthologues: chimpanzee SLC25A15 (99% identical), pig SLC25A15 (98% identical), mouse Slc25a15 (95% identical), rat Slc25a15 (94% identical), dog SLC25A15 (94% identical), guinea pig SLC25A15 (92% identical), rabbit SLC25A15 (84% identical), tropical clawed frog slc25a15.2 (77% identical), zebrafish slc25a15a (67% identical), zebrafish slc25a15b (66% identical). Paralogues in human: SLC25A2 (87% identical), SLC25A20 (32% identical), SLC25A29 (31% identical), SLC25A45 (30% identical), SLC25A12 (29% identical), SLC25A13 (28% identical), SLC25A48 (28% identical), SLC25A47 (27% identical), SLC25A21 (26% identical), UCP2 (25% identical), UCP3 (24% identical), SLC25A16 (23% identical), and 37 more.
Diseases named in the same sentence as SLC25A15 in open-access papers:
SLC25A15 is named in the same sentence as 36 diseases in open-access papers, as found by Europe PMC text mining. Sharing a sentence is not in itself a finding about the gene and the disease. The quoted sentences say what the papers report.
Hyperammonemia (20 papers, 2009 to 2025). An increased concentration of ammonia in the blood. "Mutations in the SLC25A15 gene can lead to ornithine translocase deficiency, a rare inherited metabolic disorder characterized by hyperammonemia and impaired ureagenesis." (PMID 39135799, 2024). "Hyperornithinemia–hyperammonemia–homocitrullinuria (HHH) syndrome can be diagnosed by mutations in the SLC25A15 gene and marked by elevated ammonia, homocitrulline, and ornithine levels." (PMID 39597062, 2024). "The pathogenic variants in the SLC25A15 gene, an autosomal recessive inheritance pattern, cause hyperornithinemia–hyperammonemia–homocitrullinuria (HHH) syndrome." (PMID 39597062, 2024). "Most studies on SLC25A15 have focused on its role in the transport of ornithine and its association with the genetic disorder hyperornithinemia–hyperammonemia–homocitrullinuria syndrome." (PMID 37775731, 2023). "Some mutations in the SLC25A15 gene were related to human hyperornithinemia, hyperammonemia, and homocitrullinuria syndrome because the ornithine cycle was disrupted." (PMID 35885994, 2022). "Herein, we report the case of a patient with HHH syndrome caused by two novel mutations in the SLC25A15 gene associated with recurrent otitis episodes that precipitated hyperammonemia crises." (PMID 35711415, 2022). "Variants in SLC25A15 produce a disorder of the urea cycle, hyperornithinemia-hyperammonemia-homcitrulluria, due to reduce transport of ornithine by the carrier ORC1." (PMID 33426505, 2020). "Therefore, genetic testing for SLC25A15 variants accompanied by at least one of three metabolic traits, hyperornithinemia, hyperammonemia, and homocitrullinuria, is pivotal for a definite diagnosis of HHH syndrome." (PMID 39597062, 2024). "Ornithine supplementation and protein restriction led to complete clinical recovery in patient Pat-1106 whose hyperammonemic encephalopathy was found to be due to SLC25A15-related hyperornithinemia-hyperammonemia-homocitrullinemia syndrome." (PMID 37344829, 2023). "At present, most of the studies on SLC25A15 are focused on hyperornithinemia-hyperammonemia-homocitrullinuria, and there are few reports on tumor." (PMID 35503998, 2022). "Mutations in the solute carrier family 25 member 15 (SLC25A15) gene, which encodes for ORC1, are causative of the rare autosomal recessive urea cycle disorder (UCD) called hyperornithinemia–hyperammonemia–homocitrullinuria (HHH) syndrome (OMIM 238970)." (PMID 35711415, 2022). "As another example, hyperammonemia can be induced by defects in relevant transporters, such as mitochondrial ornithine transporter 1 (SLC25A15) and y + L amino acid transporter 1 (SLC7A7)." (PMID 35736461, 2022). "Hyperornithinemia–hyperammonemia–homocitrullinuria (HHH) syndrome (OMIM # 238970), caused by mutations in ORNT1 (SLC25A15) gene, is a rare autosomal recessive disorder of the urea cycle." (PMID 31443672, 2019). "Hyperornithinemia-hyperammonemia-homocitrullinuria (HHH, MIM #238970) syndrome is a rare genetic disorder of the urea cycle (UC) caused by mutations in the SLC25A15 or ORNT1 gene (MIM*603861), which encodes for the mitochondrial ornithine carrier ORC1." (PMID 25874378, 2015). "Although pyramidal and cerebellar affections are well-described in patients with recessive pathogenic SLC25A15 variants, hyperornithinemia–hyperammonemia–homocitrullinemia (HHH) syndrome is most likely not on the list when seeing patients clinically presenting with cHSP." (PMID 32214227, 2020).
Hyperornithinemia (19 papers, 2009 to 2025). Increased concentration of ornithine in the blood. "Hyperornithinemia-hyperammonemia-homocitrullinuria (HHH) syndrome is a rare autosomal recessive urea cycle disorder resulting from a deficiency in the SLC25A15 gene, which encodes ornithine carrier 1 (ORC1)." (PMID 40710547, 2025). "The hyperornithinemia-hyperammonemia-homocitrullinuria (HHH) syndrome is a rare autosomal recessive inborn error of the urea cycle caused by mutations in the SLC25A15 gene." (PMID 35711415, 2022). "Hyperornithinemia-Hyperammonemia-Homocitrullinuria (HHH) syndrome or the ornithine translocation deficiency is the rarest autosomal recessive disorder with various genetic mutations on the SLC25A15 (ORNT1 gene), which encodes the mitochondrial ornithine transporter." (PMID 36582900, 2022).
prostate carcinoma (5 papers, 2020 to 2024). A carcinoma that arises from epithelial cells of the prostate gland. "Over-expression of SLC25A15 correlates with poor prognosis in bladder urothelial carcinoma and prostate cancer." (PMID 36313898, 2022). "SLC25A15 was involved in the regulation of cell proliferation and apoptosis in cells and over-expression can reverse the role of tumor suppressor genes in prostate cancer." (PMID 35503998, 2022). "In prostate cancer, miR-29a-3p could down-regulate the SLC25A15 expression and inhibit the progression, migration and invasion of prostate cancer cells." (PMID 36471281, 2022).
colon cancer (2 papers, 2022 to 2025). "It was stated that mutations in SLC25A15 and SLC25A32 occurred at a higher frequency in patients with colon cancer than in healthy individuals." (PMID 41465541, 2025).
colorectal cancer (2 papers, 2023 to 2024). A primary or metastatic malignant neoplasm that affects the colon or rectum. "Dual targeting of SLC6A14 and either SLC25A15 or SLC12A4 diminishes serine uptake and growth of colorectal cancer cells in vitro and in vivo, particularly in cells with compromised de novo serine biosynthesis." (PMID 38066114, 2023).
Encephalopathy (2 papers, 2022 to 2023). Encephalopathy is a term that means brain disease, damage, or malfunction. "Targeted gene sequencing for the SLC25A15 gene identified the underlying molecular cause of a complex multisystem disorder presenting with liver damage, encephalopathy and developmental delay." (PMID 36506307, 2022).
hepatocellular carcinoma (2 papers, 2024). A malignant tumor that arises from hepatocytes. "In hepatocellular carcinoma (HCC), solute carrier family 25 member 15 (SLC25A15) is hypoxia-responsive with low glutamine reprogramming, facilitating anti-PD-L1 therapy." (PMID 39484162, 2024).
brain tumours (1 paper, 2021). "Interestingly, expression of ASL, GATM, ODC, SLC25A13 and SLC25A15 is increased in tumours compared to normal brain tissue, indicating that the arginine biosynthesis pathway could be highly active in human brain tumours." (PMID 33809510, 2021).
breast carcinoma (1 paper, 2023). "Dual targeting of SLC6A14 with SLC25A15, SLC12A4, SLC1A5 and SLC38A5 also reduced growth in MCF7 and MDA-MB-231 human breast cancer cell lines." (PMID 38066114, 2023).
breast invasive carcinoma (1 paper, 2023). "In breast invasive carcinoma no predictive value was observed by SLC6A14, SLC12A4 or SLC25A15 alone, but there was a nonsignificant trend for reduced survival in SLC6A14-high combined with SLC12A4-high or SLC25A15-high expression." (PMID 38066114, 2023).
HHH syndrome (1 paper, 2012). "Mutations of the solute carrier family 25 (mitochondrial ornithine transporter) member 15 (SLC25A15) gene (previously termed ORNT1) have been shown to be correlated with the HHH syndrome." (PMID 22292090, 2012).
stomach adenocarcinoma (1 paper, 2024). "In contrast, as an another cis-target mRNA of LOC102160118, SLC25A15 is an OS- and metabolism-related gene serves as a biomarker for predicting adverse events in patients with stomach adenocarcinoma." (PMID 39681884, 2024).
thyroid tumorous (1 paper, 2022). "SLC25A15, DIRAS2, PLA2R1, and MTARC1 expression was downregulated in thyroid tumorous tissues with LNM compared thyroid tumorous tissues with NLNM, which was validated using the TCGA dataset." (PMID 36106120, 2022).
tumor (12 papers, 2018 to 2023). "IHGA can display the differential expression of SLC25A15 mRNA in tumor tissues of early- and late-stage patients in different clinical staging systems across multiple datasets." (PMID 37635767, 2023). "Nevertheless, in established serine synthesis-deficient tumor xenografts, acute silencing of SLC6A14/SLC12A4 and to a lesser degree SLC6A14/SLC25A15 reduced tumor growth and serine levels, despite a large proportion of DOX escapers." (PMID 38066114, 2023). "While specific studies on SLC25A15 in cancer are limited, exploring its potential role in tumor biology is important." (PMID 37775731, 2023). "Grade data indicate that SLC25A15 is significantly downregulated in poorly differentiated tumor tissues in TCGA-LIHC." (PMID 37635767, 2023). "Collectively these results suggest that in serine synthesis-deficient tumors, targeting SLC6A14 together with an ion exchanger/facilitator (SLC12A4) or a mitochondrial serine transporter (SLC25A15) can decrease serine uptake, leading to reduced tumor growth." (PMID 38066114, 2023). "The downregulation of SLC25A15 can facilitate pyrimidine synthesis via dihydroorotase and enhances cell proliferation and tumor growth." (PMID 36106120, 2022). "Comparative analyses of these DEPs revealed downregulated expression of specific proteins with well-established links to tumor metastasis, such as SLC25A15, DIRAS2, PLA2R1, and MTARC1." (PMID 36106120, 2022). "Further research is needed to investigate whether SLC25A15 alterations or dysregulation are associated with specific cancer types and elucidate the mechanisms by which SLC25A15 may impact tumor development and progression." (PMID 37775731, 2023). "Moreover, the results of q-RT PCR showed that CTSV, RGS4, SYT13 and NPTX1 were highly expressed in tumor tissues compared with adjacent tumor tissues, while SLC25A15, ENTPD2 and CA8 were low expressed." (PMID 36684237, 2022). "Whether SLC25A15 has other potential signaling pathways involved in tumor progression." (PMID 35503998, 2022). "SLC25A15 could reverse the tumour suppressing roles of knock‐down circFOXO3 in PCa." (PMID 31733095, 2020). "Two DEPs (SLC25A15 and PLA2R1) were also validated their expression difference between tumor and peritumoral tissues using IHC method." (PMID 36106120, 2022). "Among which, SLC25A15, RAD9A, PRF19, THOC1, and TIPIN were significantly overexpressed in tumor tissues in both the TCGA and our local cohorts." (PMID 36033441, 2022). "While ASS1 was found to be downregulated in GBM tumours and NCH644 NS cultures, the expression of ODC1, SLC25A13 and SLC25A15 was increased." (PMID 33809510, 2021). "This cell line also mostly mimicked downregulated small molecule transporters seen in tumours, e.g. NPC1L1, SLC25A15/20, SLC2A2, SLC1A1 and SLC7A2." (PMID 30176945, 2018). "In most HCC datasets, both in tumor and nontumor tissues, SLC25A15 and HNF4A are significantly positively correlated." (PMID 37635767, 2023). "Unfortunately, both the mRNA and protein expression levels of SLC25A15 was not remarkably different between tumor and adjacent normal thyroid." (PMID 34405007, 2021).
cancer (5 papers, 2017 to 2023). A tumor composed of atypical neoplastic, often pleomorphic cells that invade other tissues. "The exact involvement of SLC25A15 in cancer remains unknown; however, alterations in mitochondrial transporters and metabolism have been implicated in various aspects of cancer biology, including cell survival, proliferation, and drug resistance." (PMID 37775731, 2023). "Using physiologically relevant conditions, we found that SLC6A14 is a plasma membrane serine transporter and SLC25A15 a mitochondrial serine transporter in cancer cells." (PMID 38066114, 2023). "Our results show that dual targeting of SLC6A14 with SLC25A15 or SLC12A4 is detrimental to cancer cell proliferation, especially in the context of low de novo serine synthesis." (PMID 38066114, 2023). "They further characterize cytosolic SLC6A14 and mitochondrial SLC25A15 as mediators of adequate serine supply to sustain cancer cell proliferation." (PMID 38066114, 2023). "The association of mRNA expression of predicted target genes (PDCD6, GNG5, PHF6, MAL2, SLC25A15, PTDSS1) with clinicopathological parameters of BLCA patients were analyzed by UALCAN, containing BLCA individual cancer stages and molecular subtypes." (PMID 35503998, 2022). "Multivariate analysis indicated that transcriptional expression of predicted target genes (PDCD6, GNG5, PHF6, MAL2, SLC25A15 and PTDSS1) were significantly correlated with BLCA individual cancer stages and molecular subtypes." (PMID 35503998, 2022). "SLC25A15, also known as mitochondrial ornithine transporter 1, has not been extensively studied in the context of cancer." (PMID 37775731, 2023). "Furthermore, we performed a pan-cancer analysis of predicted target genes (PDCD6, GNG5, PHF6, MAL2, SLC25A15 and PTDSS1) by using TIMER." (PMID 35503998, 2022). "Additionally, high transcriptional expression of PDCD6, GNG5, PHF6, MAL2, SLC25A15 and PTDSS1 were significantly correlated with BLCA individual cancer stages and molecular subtypes." (PMID 35503998, 2022).
bacterial infection (1 paper, 2025). "The NEK5 and SLC25A15 genes encode proteins involved in mitochondrial function, cell-cycle progression, metabolism and tumourigenesis, but have no clear role in the immune response to bacterial infection." (PMID 40342962, 2025).
SLC25A15 also shares sentences with these, for which no sentence is quoted: urea cycle disorder (6 papers); genetic disorder (3); gastric cancer (2); bladder urothelial carcinoma (1); citrin deficiency (1); colon adenocarcinoma (1); deficiency (1); developmental delay (1); Gastric tumors (1); infection (1); ischemia (1); lysinuric protein intolerance (1); melanoma (1); metabolic disorder (1); metabolic syndrome (1); Ornithine transcarbamylase deficiency (1); ornithine translocase deficiency (1); ovarian carcinoma (1); pancreatic adenocarcinoma (1); Spasticity (1).